CENPE (centromere protein E)
Diseases named in the same sentence as CENPE in open-access papers (continued):
Sharing a sentence is not in itself a finding about the gene and the disease.
glioblastoma (1 paper, 2024). The most malignant astrocytic tumor (WHO grade IV). "Studies have shown that increased CENPE expression is linked to clinical stage and overall survival in glioblastoma, and inhibiting its expression leads to the inhibition of glioblastoma cell proliferation." (PMID 38702677, 2024).
leiomyosarcoma (1 paper, 2020). An uncommon, aggressive malignant smooth muscle neoplasm, usually occurring in post-menopausal women. "In human leiomyosarcomas (LMS), expression of UBE2C was found in 12 of 26 (46%), of CENPE in 7 of 26 (27%), of HAS2 in 7 of 26 (25%) and of CREB3L2 in 20 of 27 (74%) human leiomyosarcoma cores." (PMID 32898143, 2020).
Lissencephaly (1 paper, 2015). A spectrum of malformations of cortical development caused by insufficient neuronal migration that subsumes the terms agyria, pachygyria and subcortical band heterotopia. "Cortical disruptions that derive from mutations in genes such as NDE1, LIS1, PP4c, WDR62, CENPE, TCOF1, AGS3, VANGL2 and HTT, are classified as micro- or macro-cephaly, and/or cortical disorganization and abnormal cortical architecture, lissencephaly and simplified gyral patterns." (PMID 25729350, 2015).
myeloid leukemia (1 paper, 2021). A clonal proliferation of myeloid cells and their precursors in the bone marrow, peripheral blood, and spleen. "In our in vitro studies, knockdown of CENPE expression resulted in the suppression of proliferation of myeloid leukemia cells and reversal of cytarabine (Ara-C) chemoresistance." (PMID 34868981, 2021). "In conclusion, LIN28A inhibited the CENPE mRNA and protein production, and reduced CENPE mRNA stability in myeloid leukemia cells." (PMID 34868981, 2021). "In conclusion, the proliferation of myeloid leukemia cells was inhibited and chemoresistance was reversed after knocking down the expression of CENPE." (PMID 34868981, 2021). "Knockdown of CENPE expression led to the suppression of growth of myeloid leukemia cells and reversal of Ara-C chemoresistance." (PMID 34868981, 2021).
osteosarcoma (1 paper, 2025). A usually aggressive malignant bone-forming mesenchymal neoplasm, predominantly affecting adolescents and young adults. "This study primarily demonstrated that reduced expression of MALAT1 leads to an increased binding affinity between SRSF1 and pre-mRNA (B-MYB and CENPE), thereby regulating alternative splicing mechanisms in osteosarcoma cells." (PMID 41019082, 2025).
pancreatic adenocarcinoma (1 paper, 2018). "For validation experiments, we focused our efforts on CENPE and RRM1 because of their biological significance in pancreatic adenocarcinoma and the availability of validated small molecule inhibitors." (PMID 30323222, 2018).
primordial dwarfism (1 paper, 2017). "Other genes associated with microcephalic primordial dwarfism shown to cause defects in centrosomal and spindle microtubule function include: PCNT, CENPE and POC1A." (PMID 28334956, 2017).
scleroderma (1 paper, 2020). Scleroderma is a rare autoimmune connective tissue disorder characterized by abnormal hardening of the skin and, sometimes, other organs. "Notably, CENPE was increased in vascular progenitors and mature endothelial cells as one of the scleroderma autoantigens with IFI-16 in McMahan’s study, which supported its role in proliferation of vascular endothelial cells in our study." (PMID 32586319, 2020).
tumor (57 papers, 2009 to 2026). "Paradoxically, some SAC mutations (e.g., CENPE heterozygosity) can be both tumour predisposing and tumour suppressing, depending on cellular context." (PMID 40401507, 2025). "Centromere‐associated protein E (CENPE) has been identified as overexpressed in multiple cancers and exerts a tumour promotion function by affecting chromosome misalignment and mitosis." (PMID 40794013, 2025). "Elevated CENPE expression was associated with advanced tumour stages and lower patient survival, highlighting its potential as a prognostic marker." (PMID 40794013, 2025). "Enrichment analysis revealed that CENPE expression was linked to multiple biological functions and tumor-associated pathways." (PMID 38702677, 2024). "We also discovered that CENPE expression was associated with the tumor grade and the infection status of H. pylori." (PMID 38702677, 2024). "In the experiment, the expression profiles of tumor samples were divided into CENPE-low and CENPE-high groups and then analyzed based on hallmark gene sets, KEGG gene sets, and oncogenic signature gene sets." (PMID 35496042, 2022). "We therefore analysed the expression of the ER-regulated genes (ERGs) TFF1, GREB1 and PR, together with PLK1, Ki67, PCNA and CENPE (a centromere associated protein that accumulates in G2 phase and is involved in chromosome alignement), in treated tumours." (PMID 32792481, 2020). "Inhibition of CENPE-encoded protein CENPE (Centromere-associated protein E), a kinetochore-associated mitotic kinesin, has been shown to induce cancer cell apoptosis and tumor regression." (PMID 31426369, 2019). "Correlative analysis revealed that, in men, CTAG2 expression was strongly correlated with known lactotroph tumor aggressiveness markers implicated in the cell cycle (CENPE, AURKB, CCNB1, ADAMTS6)." (PMID 30555413, 2018). "As a mitotic cell cycle-associated gene, CENPE has an essential and positive function in the process of mitotic cytoplasmic separation, which was related to the cell cycle, and the rapid proliferation is a common characteristic of tumor cells." (PMID 37925501, 2023). "We also identified CENPE as an important oncogenic regulator in ccRCC by bioinformatics analysis of public profiling data, revealing that CENPE was found to be overexpressed in ccRCC tissues, and its elevated expression was associated with advanced tumour stages and poor clinical outcomes." (PMID 40794013, 2025). "Therefore, we evaluated the association with CENPE and the tumor microenvironment, processed the expression profiles of TCGA by the CIBERSORT algorithm, analyzed the immune cells of each GC sample, and mapped the expression profiles of 22 different immune cells." (PMID 38702677, 2024). "Indeed, the twelve UM with CENPE alterations had significantly higher genome percentages with CNAs (Mann–Whitney, P = 0.028, median 23% vs 15%), though this association is confounded since tumours with high CNA generally have more genome-wide regions of LOH." (PMID 32415113, 2020). "In certain contexts, increased whole‐chromosome mis‐segregation resulting from reduced CENPE expression can suppress tumour formation." (PMID 40401507, 2025). "Cells in which tumour suppression occurs following reduced CENPE expression were shown to have already pre‐existing, elevated basal levels of chromosome mis‐segregation that were further exacerbated by reduced CENPE expression." (PMID 40401507, 2025). "Seven genes were associated with recurrence and progression: ADAMTS6, CRMP1, PTTG, ASK, CCNB1, AURKB, and CENPE, while ADAMTS6, CRMP1, ASK, CCNB1, and CENPE were also associated with tumor recurrence and progression." (PMID 41303810, 2025). "CAKI‐1 cells transfected with sh‐CENPE led to significantly smaller tumours in nude mice compared to the control group, with reductions observed in both tumour volume and tumour weight." (PMID 40794013, 2025).
tumor (continued). "This study identified CENPE as a key promoter of ccRCC progression, driving tumour proliferation, migration, and invasion both in vivo and in vitro." (PMID 40794013, 2025). "Immunohistochemistry showed that CENPE protein levels were reduced in the tumour cells of DDR1‐positive cases of DLBCL." (PMID 40401507, 2025). "Overall, we have identified CREB1 as a positive transcriptional regulator for CENPE in ccRCC in vitro, directly binding to its promoter region and promoting its expression, thereby contributing to the upregulation of CENPE in tumour progression." (PMID 40794013, 2025). "Consistent with the public datasets, CENPE was significantly upregulated in tumour tissues compared to paracancerous tissues." (PMID 40794013, 2025). "Our findings extend this knowledge by identifying that CENPE upregulates β‐catenin levels in ccRCC cells, promoting tumour progression." (PMID 40794013, 2025). "Numerous independent analyses of gene expression databases, clinical tumour samples, and in vitro cell lines have revealed that KIF10/CENPE is overexpressed in both LUAD and LUSC forms of NSCLC." (PMID 40002279, 2025). "Immunohistochemical staining results revealed that CENPE expression was minimal in normal kidney tissues, while ccRCC tumour tissues exhibited strong positive staining for CENPE, indicating significant overexpression of the protein in the tumour." (PMID 40794013, 2025). "Paired analyses of normal and tumour tissues in these datasets further confirmed the consistent overexpression of CENPE in ccRCC tissues." (PMID 40794013, 2025). "Quantitative analysis revealed that both tumour volume and tumour weight were significantly reduced in the sh‐CENPE group compared to the control, demonstrating that CENPE knockdown effectively suppressed tumour growth in vivo." (PMID 40794013, 2025). "Taking the median value of CENPE expression, the tumor samples of GC were separated into low and high expression groups, and the differences in the degrees of expressiveness of 22 immune cells were assessed using the vioplot package." (PMID 38702677, 2024). "Researchers have found that CENPE is involved in the regulating cell proliferation, apoptosis, and migration in tumor cells." (PMID 36233060, 2022). "Intriguingly, the expression levels of CCNB1, CDC20, and CENPE in PBMCs were completely opposite to those observed in tumor tissues." (PMID 34660300, 2021). "Similar trends for the cell-cycle-associated genes (ASPM, CENPE, TPX2, TRIP13, KIF11, KIF20A) were observed with their distribution in different-grade tumors, with higher expression levels observed as tumor grade increased." (PMID 23506684, 2013). "Furthermore, IHC staining showed reduced expressions of CENPE, β‐catenin, Ki‐67 (a proliferation marker) and N‐cadherin in mouse tumour tissues with CENPE knockdown." (PMID 40794013, 2025). "Interestingly, CENPE inhibition with GSK923295 was recently described to synergize with PD-L1-targeted immunotherapy in NSCLC tumour models, which was attributed to CENPE inhibitor-mediated upregulation of PD-L1." (PMID 40002279, 2025). "Finally, an in vivo mouse model was constructed to further explore the role of CENPE in the tumour growth of ccRCC." (PMID 40794013, 2025). "Immunohistochemical (IHC) analysis of the xenograft tissues showed decreased expression of the proliferation marker Ki‐67, along with reduced levels of N‐cadherin, further supporting the notion that CENPE promotes tumour growth by enhancing cell proliferation and EMT." (PMID 40794013, 2025). "Here, we provide evidence that CENPE promotes the proliferation and metastasis of ccRCC cells by enhancing the Wnt/β‐catenin signalling pathway, which is well known for its role in promoting tumour growth and metastatic spread." (PMID 40794013, 2025).
tumor (continued). "Furthermore, It was discovered that H. pylori infection status and tumor grade were related to CENPE expression." (PMID 38702677, 2024). "Based on tumor grade, CENPE expression in grades 1 and 3 was a notable variation (P < 0.05)." (PMID 38702677, 2024). "The CENPE was upregulated while LDHA was downregulated in tumor tissues." (PMID 37925501, 2023). "For example, the factors contributed to the LDHA downregulated in tumor samples remains unclear, and the mechanism of CENPE as a carcinogenic factor positively regulating the immune cells was not clarified." (PMID 37925501, 2023). "We speculate that although CENPE is highly expressed in tumor tissues, it has a good effect on survival, which may be a protective factor for ESCC." (PMID 35496042, 2022). "High gene expression of CENPE is positively correlated with the tumor suppressor pathway." (PMID 35496042, 2022). "Our results support the idea that CENPE is a promising target for this tumor type." (PMID 33804489, 2021). "Conversely, it suggests that activation of the SAC could be a critical passage of the anti-tumor activity elicited in MB cells by CENPE inactivation." (PMID 33804489, 2021). "In a re-analysis of those data, one prominentgene-expression feature included genes regulating the cell-cycle (e.g. CCNE1,CDK1, CDC25A), and involved in DNA replication(e.g. POLE2, MCM4, TK1) andchromosome dynamics (e.g. SMC4, CENPE), ostensiblyreflecting tumor cell proliferation levels." (PMID 21629784, 2011). "Observations that Eg5 and CENPE inhibitors have been well-tolerated in patients suggest that inhibiting these kinesins in normal cells is relatively innocuous; although, on-treatment tumour biopsies would be required to confirm effective suppression of target activity." (PMID 40002279, 2025). "Notably, in these experiments, neither of the single drug treatments resulted in significant tumor growth reduction; however, the combination of MEK and CENPE inhibitors synergistically and significantly reduced tumor volume (p < 0.01, t-test) after 4 weeks of treatment in vivo." (PMID 30323222, 2018). "Key mitotic regulators, including kinases such as PLK1, AURKA, AURKB, and MPS1 and kinesins such as CENPE and Eg5, are frequently overexpressed in NSCLC and SCLC, contributing to chromosomal instability, aneuploidy, and highly proliferative tumor phenotypes." (PMID 42076055, 2026). "When classified by tumour staging and TNM system, high‐level CENPE was correlated with more advanced disease." (PMID 40794013, 2025). "An examination of tumor specimens revealed an escalation in the expression of KIF18A, in conjunction with heightened levels of CENPE, SNHG4, KIAA1841, CDCA2, and PRR11 mRNA." (PMID 38495502, 2024). "Our study found that CENPE expression is inhibited by miR-137, while KIF14 and NCAPG expression are inhibited by miR-6500-3p, and an anti-tumor effect was achieved by combining TMZ with either miR137 or miR-6500-3p." (PMID 26933822, 2016). "Notably, when CREB1 was silenced, these oncogenic effects of CENPE were significantly diminished, further supporting the essential role of CREB1 in mediating CENPE's tumour‐promoting effects in ccRCC." (PMID 40794013, 2025). "In contrast, tumours that arose as a consequence of transforming events that do not induce chromosomal instability were unaffected by CENPE‐dependent chromosome mis‐segregation." (PMID 40401507, 2025).
tumor (continued). "A gross view of collected tumours obviously revealed a smaller size in mice injected with CAKI‐1 cells transfected with sh‐CENPE than that of the negative control." (PMID 40794013, 2025). "Given the role of CREB1 in regulating CENPE, therapies that disrupt the CREB1‐CENPE axis may be particularly effective in inhibiting tumour growth and metastasis in ccRCC patients." (PMID 40794013, 2025). "Orthotopic models that more closely mimic the natural tumour environment could provide deeper insights into how CENPE and CREB1 promote tumour progression in a more physiologically relevant context." (PMID 40794013, 2025). "CENPE expression status did not correlate with the proliferative index of tumours (unpaired t‐test, p = 0.13)." (PMID 40401507, 2025). "This study analyzed the molecular mechanisms of tumor progression and poor prognosis mediated by CENPE in non-WNT/non-SHH MB." (PMID 37593739, 2023). "Although BUB1B and CENPE have not been reported to be involved in tumour immunity, their functions in the TME warrant further research." (PMID 34631565, 2021). "Aberrant upregulation of kinesin family members could lead to uncontrolled tumor growth, and hence mitotic kinesin inhibitors such as KIF11-targeted inhibitors and CENPE-targeted inhibitors have attracted great attention in drug development." (PMID 33995648, 2021). "Furthermore, SW480-derived microvesicles are enriched with CENPE, KIF15, CEP55, CCNA2, NEK2, PBK, and CDK8 that are M-phase-related transcripts involved in tumorigenesis and tumor progression." (PMID 19930720, 2009). "At the same time, immune cell infiltration analysis showed that CENPE may participate in the immune response and tumor microenvironment (TME) of non-WNT/non-SHH MB." (PMID 37593739, 2023). "Finally, the five candidate genes DNMT3B, EXO1, MCM10, CENPF and CENPE were combined in a new prognosis tool, Gene Expression Classifier or GEC, that stratifies patients according to the number of activated genes in the corresponding tumour (activation status ON)." (PMID 37592220, 2023). "To explore the correlation between the expression level of CENPE and tumor immune response, we first used CIBRSORT to evaluate the differences in immune cell infiltration in non-WNT/non-SHH MB with high and low expression of CENPE." (PMID 37593739, 2023).